IRF7 (interferon regulatory factor 7)
Diseases named in the same sentence as IRF7 in open-access papers (continued):
Sharing a sentence is not in itself a finding about the gene and the disease.
viral infection (continued). "By virus infection, activations of some certain PRRs such as TLR3, RIG-I and MDA5 result in the phosphorylation and nuclear translocation of IRF3 and IRF7." (PMID 25759845, 2015). "Viral infection is sensed by endosomal Toll-like receptors (TLRs), which signal to activate NF-κB, IFN-regulatory factor 3 (IRF3), IRF7, and downstream transcription of cytokine and IFN-α/β genes." (PMID 25360880, 2014). "Virus infection results in the coordinate activation of NF-κB, ATF-2/c-Jun, IRF3, and IRF7 that assemble sequentially on this IFN-β enhancer region." (PMID 24722640, 2014). "Similar to IRF3, the transcription factor IRF7 is another key regulator of type I IFN induction and is critical for host defense against virus infections." (PMID 24743339, 2014). "In particular, interferon stimulated pathways such as those including RSAD2, IRF7, MX1, OAS3, MDA-5, RIG-I and others are incorporated and thought to drive both innate and, to a lesser degree, adaptive immune responses to viral infection." (PMID 23326326, 2013). "Of the IRF family, IRF7 plays an important role in anti-viral responses and can be activated in a similar manner to IRF3 during viral infection." (PMID 23555825, 2013). "Activation of IRF7 after viral infection resembles IRF3 activation, and involves the direct phosphorylation of IRF7 by TBK1 and IKKε." (PMID 23758787, 2013). "RIG-1 and MDA-5 are cytosolic PRRs that sense viral infections through recognition of viral dsRNA leading to activation of TBK and IKK-α and result in induction of type I IFNs through activation of IRF-7 transcription factor." (PMID 23626859, 2013). "In conclusion, virus infection of airway epithelia induces, via a RIG-I/MAVS/IRF7 dependent pathway, both type I and III IFNs which drive two completely overlapping and redundant amplification loops to upregulate ISGs and protect from influenza infection." (PMID 24278020, 2013). "Upon activation in response to TLR agonists and viral infection, IKKε phosphorylates IRF3 and IRF7 and triggers IRF3/IRF7 nuclear translocation, which results in the up-regulation of type I IFN expressions." (PMID 22783275, 2012). "Here, we show that peak levels of transcription correspond to transient recruitment of IRF7 and IRF3 to the promoters during virus infection." (PMID 22685561, 2012). "A related transcription factor of the IRF family, IRF7, also plays an important role in anti-viral responses and can be activated in a similar manner to IRF3 during viral infection." (PMID 21931555, 2011). "IRF7 is required for high levels of IFN gene expression, but it is present at only low levels prior to virus infection." (PMID 21677781, 2011). "The induction of type I IFNs is the earliest cellular immune response initiated to combat viral infections and is coordinated by the activation of transcription factors such as interferon regulatory factor (IRF)-3, IRF7, and NFκB downstream of PRR activation." (PMID 21436888, 2011). "In the cellular response to virus infection, IRF3 and IRF7 play a predominant role in the transcriptional induction of the type I IFN (IFN-I) family, comprised of a single IFNβ gene and a cluster of IFNα genes." (PMID 21994600, 2010). "Interferon regulatory factors (IRF)-3 and IRF-7 are master transcriptional factors that regulate type I IFN gene (IFN-α/β) induction and innate immune defenses after virus infection." (PMID 19798431, 2009). "Host recognition of viral infection normally activates multiple evolutionarily conserved signaling pathways, such as NF-κB and the IFN-regulatory factors 3 and 7 (IRF3 and IRF7)." (PMID 18617992, 2008). "Besides, compared all other T-cell subtypes, the CD38+HLA-DR+ T cells exhibited higher expression levels of interferon regulatory factors (IRF1 and IRF7) and T cell factor -7 (TCF7), indicating the host’s immune response against viral infection." (PMID 40370439, 2025).
viral infection (continued). "Overall, IRF7 enhanced the otherwise limited level of IFNB induction in Huh7.5 and Huh7 cells not only upon artificial poly(I:C) stimulation but also in the context of viral infection." (PMID 40407345, 2025). "For instance, Interferon Regulatory Factor 7 (IRF7) is a key transcription factor that plays a central role in regulating the expression of type I interferons (IFNs), which are critical components of the innate immune response to viral infections." (PMID 41012626, 2025). "In chickens, where IRF3 is absent, IRF7 is utilized to reconstitute the corresponding IFN signalling pathway in response to viral infection." (PMID 40108733, 2025). "The results obtained from these two independent studies showed that the immune response to the live attenuated yellow fever vaccine is preceded by an orchestrated overexpression of key transcription factors, including STAT1 and IRF7, which can elicit a broad and long-lasting immune response." (PMID 38932312, 2024). "IRF7 is essential for the expression of type I IFNs throughout all phases of viral infection, and therefore, the lack of IRF7 facilitates viral infection and in some cases of severe influenza is even life-threatening." (PMID 38932312, 2024). "In the case of viral infection, Lgals3bp forms complex with Traf6 or Traf3, and subsequently recruits TAK1 and TBK1, which then signal the translocation of the transcription factors NF-κB, IRF3, and IRF7 from the cytoplasm to the nucleus." (PMID 38279161, 2024). "In addition, the virus stops the host cell from identifying and reacting to the viral infection by suppressing IRF3 and IRF7 activation." (PMID 38355695, 2024). "Indeed, many interferon‐related genes upregulated during viral infection in rats were found to be downregulated by PTS in this study (e.g., Oas1a, Oas2, Irf7, Ifi27, Lgals3 bp)." (PMID 39562169, 2024). "In some virus infections, the antiviral effect is independent of IFN-I, IRF3, IRF5 or IRF7, and deficient mice survive the infection." (PMID 37737190, 2023). "Our results have demonstrated a novel negative feedback mechanism that restricts IRF7 activation during virus infection." (PMID 38043800, 2023). "Moreover, the upregulation of expression of TLR7, MyD88, IRF7, IRAK4, TRAF6, and TRAF3 induced by viral infection were significantly suppressed under FFYH treatment both in vitro and in vivo." (PMID 37089926, 2023). "Select genes that were highly expressed in COVID-19(+) TV specimens compared to COVID-19(+) PU and COVID-19(-) PU control groups play a central role in regulation of innate immune responses and defense to viral infection, including CARD8, IL1A, CD274, TRIM35, IRF7, and IFIH1." (PMID 37026002, 2023). "The host immune targets such as TLR7, IRF7, IRF5, and IL6, which are involved in the immune response against viral infections, and the sex-specific targets such as AR and ESSR were taken to investigate any possible link with the SARS-CoV-2 host receptors ACE2 and TMPRSS2." (PMID 36992366, 2023). "However, our results show that viral infection or genetic knockout of lincRNA‐EPS facilitates PKR‐STAT1 signaling axis induced antiviral genes such as Mx1, Oas2, Ifit2, and Irf7, while inhibits phosphorylation of TBK1 and IRF3, as well as the IFN‐β induction." (PMID 35312140, 2022). "To investigate the mechanism by which ubiquitination‐resistant mutation restricted the transcriptional activity of IRF7, we first analyzed the subcellular localization of IRF7‐K375R with or without viral infection." (PMID 35792897, 2022).
viral infection (continued). "Among the upregulated ISGs, 27 ISGs, including IRF1, IRF7, IFITM1, and IFITM3, play antiviral roles in different stages of virus proliferation, thus inhibiting or delaying the process of virus infection by interacting with other proteins or ISGs to form a complex protein–protein interaction network." (PMID 35401515, 2022). "IRF7 is the main regulator of type I interferon (IFN) expression, which can form dimers with IRF3, and type I IFN expression was impaired in Irf7−/−plasmacytoid dendritic cell precursors (pDCs) or mouse embryonic fibroblast (MEFs) upon virus infection." (PMID 36618529, 2022). "Given the apparent specificity of MNDA for IRF7 induction, and the cell type-specific expression of MNDA, this PYHIN could be a key target either to boost type I IFN during a viral infection, or to inhibit dysregulated type I IFN during autoimmunity." (PMID 35013241, 2022). "The induction of MVP expression by viral infection upregulates type-I interferon production by enhancing the expression of IRF7 (interferon regulatory factor 7), but not IRF3 (interferon regulatory factor 3)." (PMID 35681764, 2022). "IRF7 is a key regulator for both type I and type III IFNs during viral infections." (PMID 34758885, 2021). "IRF7 has a key role for the production of both type I and type III IFNs during viral infections." (PMID 34758885, 2021). "Moreover, the VP35 protein of Ebola virus (EBOV) interacts with IKKε and TBK1 during the early phase of viral infection; this physical interaction with IKKε further prevents the interaction of IKKε with IRF3, IRF7, and MAVS214." (PMID 34782737, 2021). "IRF-7 is an IFN-inducible protein, up-regulated by autocrine signaling through the IFN-α/β receptor (IFNAR), that promotes further production of type I IFN after viral infection in fibroblasts." (PMID 32373120, 2020). "A ligase within the PIAS family is responsible for the sumoylation of IRF3 and IRF7 observed after a viral infection, leading to the negative regulation of type I IFN gene expression, and PIAS1 is a mediator of IRF7 sumoylation." (PMID 33192313, 2020). "As spine numbers were not changed by virus infection in Irf-7−/− mice, cognitive impairment seems to be independent of the overall spine number but on the relative number of spines." (PMID 32951602, 2020). "Exogenous rTRAIL could partially restore the expression of IRF3, IRF7, and IFN-β at early stage of viral infection (0.5–2 dpi, respectively) (compare gray column to grid column)." (PMID 32636833, 2020). "In general, Irf-7−/− mice showed increased anxiety-related behavior as compared to non-infected WT mice regardless of virus infection." (PMID 32951602, 2020). "A recent study discovered that chicken IRF7 constitutes IRF3 to mediate the relevant signaling function; thus, like in mammals, the chicken cGAS-STING-TBK1-IRF7 signaling pathway plays a critical role in circumventing virus infection." (PMID 32660114, 2020). "Moreover, ISG15, STAT1, IRF7 and DDX58 were identified as the hub genes that play a pivotal role in response to viral infection and their expression were up-regulated with ageing." (PMID 30641486, 2019). "Furthermore, during viral infection in mice, TET2 is recruited by CXXC5 to the Irf7 promoter to induce Irf7 hypomethylation and expression in pDCs, resulting in the onset of an antiviral response." (PMID 31214161, 2019). "IRF3 and IRF7 are the key regulators of type I and III IFNs during viral infections." (PMID 29515574, 2018). "Similar to the involvement of RLR-mediated type I IFN expression, IRF3 and IRF7 also contribute to the signaling pathways downstream of cytosolic DNA sensing and endosomal DNA/RNA recognition for the inductions of IFN-α and IFN-β during virus infection." (PMID 30671058, 2018).
viral infection (continued). "The significant downregulation of interferon signature genes, such as Adar (DRADA), Ddx58 (RIG-I), Ddx60 (DDX60), Stat1 (STAT1), Ifih1 (MDA5), Trim25 (TRIM25), Irf7 (IRF7), and Irf9 (IRF9) in infected Cd47−/− NK cells is consistent with the impaired Cd47−/− NK cell response to viral infection." (PMID 30643501, 2018). "Similar to IRF3, phosphorylation-activated IRF7 undergoes nucleus translocation and then cooperates with activated IRF3 to bind the promoter regions of IFN genes for the expression initiation following viral infection." (PMID 28286505, 2017). "Considering that interferon expression is mainly IRF3/IRF7-mediated while expression of TNFα and CXCL8 is mainly NFκB-mediated, it appears that azithromycin predominantly affects IRF signalling pathways after viral infection." (PMID 27350308, 2016). "Interestingly, the activation of both IRF3 and IRF7 in mammals requires virus-induced phosphorylation, coordinating the appropriate initiation of IFN responses during virus infection." (PMID 27656183, 2016). "Both IRF3 and IRF7 play distinct and essential roles in the IFN-α/β response to virus infection." (PMID 25798928, 2015). "IRF3 and IRF7, two key transcription factors that modulate type I IFN expression, are phosphorylated, undergo homo/heterodimerization, and translocate into the nucleus upon viral infection." (PMID 26186542, 2015). "Meanwhile, virus infection triggers SUMOylation of IRF7 and this modification negatively regulated virus-stimulated interferon transcription." (PMID 25907774, 2015). "Cardiac myocytes was reported to produce higher basal IRF-7 without viral infection through the Jak-STAT pathway activated with preexisting IFN-β for instant antiviral response." (PMID 24587086, 2014). "Although further analysis of the cell types responsible for constitutive IRF7 expression in bats is required, a constitutively expressed IRF7 in a broad range of cells and organs may result in faster and stronger IFN production upon viral infection." (PMID 25100081, 2014). "This signaling likely occasion induction of the IRF-7 gene without viral infection as a priming effect." (PMID 24587086, 2014). "Because most viruses induce IFN-I and in turn IRF7 expression and can activate the resulting IRF7 protein effectively, Oasl1 KO mice are expected to be resistant to most viral infections that do not produce viral effectors to degrade the function of IRF7." (PMID 23874199, 2013). "Recently, we showed that 2′–5′ oligoadenylate synthetase (OAS)-like 1 (OASL1), an IFN-stimulated gene (ISG), is a novel translation inhibitor of IRF7, the IFN-inducible IFN-I master TF, and negatively regulates robust IFN-I production during acute viral infections." (PMID 23874199, 2013). "In the early phase of viral infection, IFN-regulatory factor 3 (IRF3) and IRF7 are phosphorylated at specific serine residues, resulting in the homodimerization or heterodimerization of the IRF3 and IRF7." (PMID 23118935, 2012). "The low basal expression of IRF7 is thought to account for the stochastic expression of IFNβ following virus infection, a phenomenon that does not occur in cells primed with IFN-I." (PMID 21994600, 2010). "Since the interferon regulatory factor-3 (IRF-3) contributes to a first line of defence against virus infection, we investigated whether the BTV infection of mammalian cells results in the activation of IRF-3 and related IRF-7." (PMID 21134281, 2010). "Irf7 was also increased in the trigeminal ganglia and the brain stem at 12 hpi and 1 dpi in both strains, suggesting a systemic response to the viral infection, as the virus had not yet reached these compartments." (PMID 20806060, 2010). "In addition, upon viral infection, TRAF6 forms a complex with IRF7 together with MyD88, IRAK4, and IRAK1." (PMID 19479062, 2009). "In contrast, lack of IRF3 or that of IRF7 resulted in significant reduction or abrogation of the viral infection-induced type I IFN production, respectively." (PMID 19479062, 2009).
viral infection (continued). "However, we did not include IRF7 in the current study due to its limited intracellular abundance and its primary function during the later stages of viral infection." (PMID 37680466, 2023). "Decreased phosphorylation of IRF7 and TBK-1 in CD14dimCD16+ monocytes, cDC1, and cDC2 from older donors impairs the production of IFN downstream of TLR7/8 and RIG-I pathways in primary antiviral responses and the ability of these cells to respond quickly to viral infection." (PMID 35849213, 2022). "Interestingly, the relative expression level of antiviral response genes was similar to that of immune-related genes in mucosal tissues such as IRF7, which is a master transcriptional factor that regulates IFN gene induction and innate immune response after virus infection." (PMID 33897703, 2021). "However, corneal endothelial cells are not professional APCs, and it is not clear how IRF7 can contribute to the protection from viral infections." (PMID 34389779, 2021). "Collectively, these data indicated that in a host with impaired with antiviral immunity (i.e. IRF7-/- mice), IL-33 and HMGB1 contribute to increased ILC2 numbers, type-2 cytokine production and the development of ASM remodelling in response to an early-life viral infection." (PMID 32658914, 2020). "Our results may suggest that chicken IRF7 participates in mediating IFNB (but not IFNA) gene induction upon viral infection, and in controlling the basal level of IFNA (but not IFNB) gene expression in the fibroblast." (PMID 26186542, 2015). "Sequence differences in the MyD88 binding domain of bat and human IRF7 led to the hypothesis that there may be functional differences in the activation of bat IRF7 and the regulation of the IFN response that may contribute to the ability of bats to resist the clinical outcomes of viral infection." (PMID 25100081, 2014). "Although the transcription factors IRF-3 and IRF-7 are considered master regulators of type I interferon (IFN) induction and IFN stimulated gene (ISG) expression, Irf3−/−×Irf7−/− double knockout (DKO) myeloid dendritic cells (mDC) produce relatively normal levels of IFN-β after viral infection." (PMID 23300459, 2013). "Similarly, although IRF-3 binding at sites B and D was not optimal relative to IRF-7, it was able to bind at these sites with adjusted orientations, resulting in transcription upon viral infection." (PMID 21698143, 2011). "However, IRF5 and IRF7 overexpression is not sufficient to completely restore IFN pathway and only partially rescued cells from viral infection due to deficiency of other important ISGs." (PMID 22194884, 2011). "Interestingly, the higher expression of genes of the IFN pathway like the transcription factors STAT1 and IRF7 as well as PKR, and IFN-β in IFN-DC resembles the expression pattern of plasmacytoid DC that are the major type I IFN producers during viral infections." (PMID 17894866, 2007). "Although IRF7 may not be mediating the IFNβ induced expression of EphB2, the ablation of IRF7 alone does induce transcription of IRF3, the long-non-coding RNA HEAL and NF-kB, three factors implicated in viral infection and inflammation." (PMID 40588746, 2025). "IRF7 has multiple functions, as the vital step of the signaling pathway in IFN-I/III induction, the function and regulatory mechanism of IRF7 is important, which may help in understanding how to protect the host to reduce viral infection and maintain body balance." (PMID 37638030, 2023). "Interestingly, only minor to moderate reduction in the induction of IRF7, IRF1, VIPERIN, IFIT5, and CMPK2 was observed at 24 hpi, probably reflecting the involvement of IFN-independent mechanisms in regulating the induction of these genes at late stages of the viral infection cycle." (PMID 35891486, 2022).